EIF2S1 (eukaryotic translation initiation factor 2 subunit alpha)
Description:
Member of the eIF2 complex that functions in the early steps of protein synthesis by forming a ternary complex with GTP and initiator tRNA. This complex binds to a 40S ribosomal subunit, followed by mRNA binding to form a 43S pre-initiation complex (43S PIC). Junction of the 60S ribosomal subunit to form the 80S initiation complex is preceded by hydrolysis of the GTP bound to eIF2 and release of an eIF2-GDP binary complex. In order for eIF2 to recycle and catalyze another round of initiation, the GDP bound to eIF2 must exchange with GTP by way of a reaction catalyzed by eIF2B. EIF2S1/eIF2-alpha is a key component of the integrated stress response (ISR), required for adaptation to various stress: phosphorylation by metabolic-stress sensing protein kinases (EIF2AK1/HRI, EIF2AK2/PKR, EIF2AK3/PERK and EIF2AK4/GCN2) in response to stress converts EIF2S1/eIF2-alpha in a global protein synthesis inhibitor, leading to an attenuation of cap-dependent translation, while concomitantly initiating the preferential translation of ISR-specific mRNAs, such as the transcriptional activators ATF4 and QRICH1, and hence allowing ATF4- and QRICH1-mediated reprogramming. EIF2S1/eIF2-alpha also acts as an activator of mitophagy in response to mitochondrial damage: phosphorylation by EIF2AK1/HRI promotes relocalization to the mitochondrial surface, thereby triggering PRKN-independent mitophagy.
Synonyms: eIF-2A; eIF-2alpha; EIF2A; EIF-2; EIF2
Tractability: Small molecule: a structure with a bound ligand is known; a high-quality ligand is known; it has a binding pocket of medium quality. PROTAC: ubiquitination databases record sites on it; its protein half-life has been measured; a small molecule that binds it is known.
Target class: Other nuclear protein
Gene: Protein-coding gene on chromosome 14 (67,360,011 to 67,386,516, forward strand). Ensembl gene ENSG00000134001.
Subcellular location: Cytoplasm, Stress granule; Cytoplasm, cytosol; Mitochondrion
Subcellular location (Human Protein Atlas): Cytosol
Pathways (Reactome):
Metabolism of proteins: Formation of the ternary complex, and subsequently, the 43S complex; GTP hydrolysis and joining of the 60S ribosomal subunit; L13a-mediated translational silencing of Ceruloplasmin expression; Recycling of eIF2:GDP; Ribosomal scanning and start codon recognition; Translation initiation complex formation
Cellular responses to stimuli: Cellular response to mitochondrial stress; PERK regulates gene expression; Response of EIF2AK1 (HRI) to heme deficiency; Response of EIF2AK4 (GCN2) to amino acid deficiency
Immune System: PKR-mediated signaling
Transport of small molecules: ABC-family protein mediated transport
Gene Ontology:
Molecular function: cap-dependent translation initiation factor activity; IRES-mediated translation initiation factor activity; protein binding; ribosome binding; RNA binding; translation initiation factor activity; nucleic acid binding
Biological process: HRI-mediated signaling; mitophagy; PERK-mediated unfolded protein response; regulation of translation in response to endoplasmic reticulum stress; response to endoplasmic reticulum stress; translational initiation; cellular response to amino acid starvation; cellular response to oxidative stress; cellular response to UV; negative regulation of translational initiation in response to stress; regulation of translational initiation; stress granule assembly; cellular response to heat; positive regulation of type B pancreatic cell apoptotic process; response to kainic acid; response to manganese-induced endoplasmic reticulum stress
Cellular component: cytosol; eukaryotic translation initiation factor 2 complex; extracellular exosome; membrane; mitochondrion; cytoplasm; cytoplasmic stress granule; eukaryotic 48S preinitiation complex; glial limiting end-foot; nucleus; synapse; translation initiation ternary complex
Genetic constraint (gnomAD): Loss-of-function variants: 2 observed, 23.47 expected, observed/expected ratio (o/e) 0.0852, 90% interval 0.034 to 0.27. The synonymous counts are far from expectation, so gnomAD's model fits this gene poorly and the ratio says little. Missense variants: 149 observed, 322.45 expected, observed/expected ratio (o/e) 0.46, 90% interval 0.4 to 0.53. Synonymous variants: 77 observed, 108.94 expected, observed/expected ratio (o/e) 0.71, 90% interval 0.59 to 0.85.
Homologues: Orthologues: chimpanzee EIF2S1 (100% identical), macaque EIF2S1 (100% identical), dog EIF2S1 (99% identical), guinea pig EIF2S1 (99% identical), mouse Eif2s1 (99% identical), pig EIF2S1 (99% identical), rat Eif2s1 (99% identical), zebrafish eif2s1b (94% identical), tropical clawed frog eif2s1 (94% identical), zebrafish eif2s1a (94% identical), rabbit EIF2S1 (92% identical), Drosophila melanogaster eIF2alpha (62% identical), and 1 more.